WFDC1 (WAP four-disulfide core domain 1)
Diseases named in the same sentence as WFDC1 in open-access papers:
WFDC1 is named in the same sentence as 26 diseases in open-access papers, as found by Europe PMC text mining. Sharing a sentence is not in itself a finding about the gene and the disease. The quoted sentences say what the papers report.
melanoma (5 papers, 2017 to 2022). A malignant, usually aggressive tumor composed of atypical, neoplastic melanocytes. "Using an in silico cohort of IFN-treated melanoma tissues, we validated a differentially expressed 9-gene core of DEGs, out of which four genes had a predictive power for efficacy: WFDC1, HSPB7, HSF1, and MT2A." (PMID 35269844, 2022). "In a significant proportion of melanomas, WFDC1 is downregulated by hypermethylation and has been shown to inhibit expression of DKK1, a known WNT signaling inhibitor." (PMID 35269844, 2022). "The drug efflux transporter ABCB5 (ATP-binding cassette, sub-family B (MDR/TAP member 5) is another controller of IL-8 expression in melanoma cells through a mechanism that involves whey acidic protein 4-disulphide core domain 1 (WFDC1/ps20) and Wnt pathway." (PMID 35011682, 2021). "Of note, several of the other genes with decreased expression upon knockdown of Tfap2a have been reported in the literature as activated (Aldh1a3, Igf2bp1, Ephb2, Pbk) or downregulated (Qpct, Wfdc1) in melanoma." (PMID 28249010, 2017). "Evaluation of the predictive power of this novel signature in silico on an ICI-treated melanoma patient cohort extracted from GEO and EGA databases, revealed WFDC1, EFNA3, DDX10, and PTBP1 as marker genes." (PMID 35269844, 2022). "From this perspective, it is of note that the IFN therapy and the ICI therapy predictive genes of our IFN resistance DEGs overlapped by three genes, WFDC1, SOX4, and BCAN, strongly suggesting a connection between the two pheno-/geno-types of melanoma: IFN and ICI resistance." (PMID 35269844, 2022). "Our in silico analysis of IFN-treated melanoma tissues of TCGA revealed the differential expression of five members of our 79 IFN-res DEGs in IFN-treated melanoma tissues: IRG SOX4 and non-IRGs WFDC1, BCAN, RPE65, and MAPT." (PMID 35269844, 2022).
ovarian carcinoma (3 papers, 2018 to 2023). A malignant neoplasm originating from the surface ovarian epithelium. "The transcripts, in particular WFDC1 and IL-17D, encode secreting factors that not only limit the metastasis of ovarian cancer, but also remodel the tumor immune microenvironment towards tumor suppression." (PMID 29548303, 2018). "Oncomine database analysis revealed that in the Anglesio cohort (GSE12172), the expression of WFDC1 was significantly lower in metastatic sites of ovarian cancer compared with primary sites (P = 0.014)." (PMID 29548303, 2018). "Results showed that the expression of WFDC1 (P = 0.0016, hazard ratio (HR) = 0.66 (0.51–0.86)) and IL-17D (P = 0.019, HR = 0.7(0.52–0.95)) was positively correlated with overall survival of ovarian cancer patients in TCGA dataset." (PMID 29548303, 2018). "The steady-state levels of these seven transcripts were assessed in two SORBS2-knockdown ovarian cancer cell lines and we identified the mRNAs of two genes, WFDC1 and IL-17D, as exhibiting reduced steady-state levels upon SORBS2 knockdown in both cell lines." (PMID 29548303, 2018). "Immunohistochemistry analysis revealed that in ovarian cancer specimens with high SORBS2 expression, expression of WFDC1 and IL-17D was also reduced in both primary and metastatic foci of ovarian cancer." (PMID 29548303, 2018). "Given that SORBS2 knockdown reduced the stability and subsequent abundance of WFDC1 and IL-17D transcripts, we attempted to characterize the functional roles of these two genes in metastatic colonization of ovarian cancer cells." (PMID 29548303, 2018). "As WFDC1 and IL-17D are secreted factors and are reported to be immunomodulatory, we further focused on the immunomodulatory role of these two genes in ovarian cancer metastasis." (PMID 29548303, 2018). "In detail, reconstituting the expression of either WFDC1 or IL-17D or a combination of both in SORBS2-knockdown ovarian cancer cells significantly reduced the number of metastatic nodules and ascites volume compared with control SORBS2-knockdown ovarian cancer cells in vivo." (PMID 29548303, 2018). "Moreover, we examined the relative concentrations of WFDC1 and IL-17D in the ascites of ovarian cancer patients in low and high SORBS2 tissues." (PMID 29548303, 2018). "Thus, SORBS2-bound transcripts of WFDC1 and IL-17D served as potent metastatic suppressors in ovarian cancer." (PMID 29548303, 2018). "Moreover, the in vivo metastatic colonization potential of SORBS2-depleted ovarian cancer cells was also remarkably reduced after overexpression of either WFDC1 or IL-17D or a combination of them." (PMID 29548303, 2018). "Moreover, in an immuno-proficient model, we also found that WFDC1 and IL-17D could potently suppress ovarian cancer metastasis and are able to inhibit the accumulation of tumor-promoting myeloid cells." (PMID 29548303, 2018). "We observed that stable overexpression of either WFDC1 or IL-17D or a combination of both significantly decreased the invasive capacity of SORBS2-depleted ovarian cancer cells compared with control, revealed by Transwell chamber analysis and wound healing analysis." (PMID 29548303, 2018). "As WFDC1 and IL-17D are secreted factors released by SORBS2-low ovarian cancer cells, we wondered whether they have any impact on the tumor microenvironment upon ovarian cancer metastasis." (PMID 29548303, 2018).
prostate carcinoma (3 papers, 2012 to 2024). A carcinoma that arises from epithelial cells of the prostate gland. "For instance, WFDC1 is implicated in prostate cancer, where it modulates the COX-2 pathway and influences immune cell activities, potentially serving as a tumor suppressor." (PMID 39296934, 2024). "For example, WFDC1 is highly expressed in prostate cancer, and WFDC2 shows abnormal expression in various tumor cells." (PMID 39296934, 2024). "Conversely, WFDC1’s expression is often reduced in prostate cancer stroma, suggesting its potential role in cancer suppression." (PMID 39296934, 2024). "WFDC1 is a tumor suppressor frequently lost in breast and prostate cancers, hepatocellular carcinoma, and Wilms’ tumor." (PMID 35269844, 2022). "WFDC1 is a multifunctional which can inhibit CD8+ T cells, NK cells, and their ability to kill prostate cancer cells." (PMID 39296934, 2024). "Currently, WFDC protein family members, including WFDC1 and WFDC2, have been studied in relation to prostate cancer." (PMID 39296934, 2024). "Furthermore, it was also been noted that WFDC1 inhibits the expansion of CD8+ T cells and NK cells in the prostate cancer microenvironment and their ability to kill cancer cells." (PMID 39296934, 2024).
fibrosarcoma (2 papers, 2013 to 2018). A malignant mesenchymal fibroblastic neoplasm affecting the soft tissue and bone. "Previous reports have demonstrated that WFDC1 expression was dramatically downregulated in highly prolific mesenchymal cells and in a number of cancers, including fibrosarcomas, and in tumors of the lung, bladder, prostate, and brain." (PMID 29548303, 2018). "WFDC1 (whey acidic protein four-disulfide core domain 1), a secreted protease inhibitor, and has been found it to be down-regulated in various cancers including fibrosarcomas, lung, bladder, and brain tumors." (PMID 23502471, 2013).
age-related macular degeneration (1 paper, 2022). Age-related loss of vision in the central portion of the retina (macula), secondary to retinal degeneration. "As a serine protease inhibitor, mediator of endothelial cell migration and promoter of angiogenesis, its enrichment in the RPE and specifically, the macula, may suggest a role for WFDC1 in age-related macular degeneration, in which neovascularization beneath the macula is characteristic." (PMID 36506320, 2022).
bladder cancer (1 paper, 2025). "Our colocalization analysis indicates that genetic variants in the WFDC1 locus may play a key role in bladder cancer risk." (PMID 40740240, 2025). "The colocalization analysis revealed that, among the 115 plasma proteins associated in the Olink dataset, three proteins - SLURP1, LY6D, and WFDC1 - exhibited strong evidence of colocalization with bladder cancer risk loci (PP.H3+PP.H4 values ~0.9999, 0.9998, and 0.758, respectively)." (PMID 40740240, 2025). "Our MR and colocalization analyses from the Olink dataset also highlighted WFDC1 as a potential bladder cancer target (meeting the PP.H3+H4 ≥ 0.7 criterion)." (PMID 40740240, 2025). "Subsequent colocalization analysis highlighted SLURP1, LY6D, WFDC1, NOV, and GSTM3 as being closely linked to bladder cancer occurrence." (PMID 40740240, 2025). "In summary, through a proteome-wide large-scale two-sample MR analysis combined with colocalization analysis, we identified SLURP1, LY6D, WFDC1, NOV, and GSTM3 as potential plasma proteins associated with bladder cancer." (PMID 40740240, 2025). "A total of 199 plasma proteins were found to be significantly associated with bladder cancer risk, among which five proteins (SLURP1, LY6D, WFDC1, NOV, and GSTM3) emerged as core candidate targets." (PMID 40740240, 2025). "In the context of bladder cancer, WFDC1 might paradoxically promote tumor invasion, possibly by enhancing protease activity or altering inflammatory regulation, despite its tumor-suppressive role observed in other settings." (PMID 40740240, 2025). "On the other hand, our findings indicate that the genes SLURP1, LY6D, and WFDC1 may influence bladder cancer development through more indirect or context-specific pathways, rather than through direct causal mechanisms detectable by MR alone." (PMID 40740240, 2025). "Thus, our findings suggest future studies should explore WFDC1 interactions within broader cancer-related pathways, possibly incorporating higher-resolution datasets or integrated multi-omics approaches to better capture its context-specific roles in bladder cancer." (PMID 40740240, 2025).
brain cancer (1 paper, 2022). A primary or metastatic malignant neoplasm affecting the brain. "Previous research has reported that WFDC1 expression was considerably downregulated in mesenchymal cells in brain cancer." (PMID 35328072, 2022).
breast carcinoma (1 paper, 2018).
emphysema (1 paper, 2025). "Of these, protein FAM177A1 and adiponectin demonstrated the strongest positive associations with percent emphysema, while ROBO2 and WAP four-disulfide core domain protein 1 (WFDC1) demonstrated the strongest inverse associations." (PMID 40616090, 2025).
gastric cancer (1 paper, 2011). A primary or metastatic malignant neoplasm involving the stomach. "Consistent with its tumor suppressor potential, ectopic expression of latexin induced differential expression of several tumor related genes, including Maspin, WFDC1, SLPI, S100P, and PDGFRB, in gastric cancer cells." (PMID 21466706, 2011).
glioma (1 paper, 2024). A benign or malignant brain and spinal cord tumor that arises from glial cells (astrocytes, oligodendrocytes, ependymal cells). "At sites of blood-brain barrier disruption, such as gliomas, WFDC1 may be highly expressed among endothelial cells interacting with platelets." (PMID 39190500, 2024).
preeclampsia (1 paper, 2024). Preeclampsia is a hypertensive disorder of pregnancy that is characterized by new-onset hypertension with proteinuria presenting after 20 weeks of gestation, and depending on mild or severe forms may initially present with severe headache, visual disturbances, and hyperreflexia. "For instance, studies on WFDC1 in preeclampsia are limited, and existing research only measures differences in WFDC1 protein expression between patients and healthy controls, without evaluating its diagnostic or prognostic value." (PMID 39296934, 2024). "In patients with preeclampsia, WFDC1 may be valuable, which can provide the value of diagnosis and prognosis, according to the elevated expression of WFDC1 at the protein level." (PMID 39296934, 2024). "Therefore, follow-up studies may further explore the role of the different gene expressions in the pathogenesis of the disease, or determine the prognostic value of the expression of WFDC1 in preeclampsia." (PMID 39296934, 2024). "They observed that the expression of several genes, including FN1, MMP9, WFDC1, BIRC5, CAV1, GATA1, and E2F1, differed between healthy pregnant women and those with preeclampsia." (PMID 39296934, 2024).
prostate tumors (1 paper, 2025). "For example, WFDC1 is downregulated in the stroma of prostate tumors, regulates the COX-2 pathway, and mediates immune cell interactions—suggesting a tumor-suppressive role." (PMID 40350979, 2025).
tumor (15 papers, 2011 to 2025). "WFDC1 (also known as ps20) is associated with tumor growth suppression and metastasis inhibition." (PMID 40740240, 2025). "Additionally, WFDC1 has been found to be significantly down-regulated in cancer-associated fibroblasts (CAFs), which are cells in the tumor microenvironment that contribute to cancer development and progression." (PMID 40740240, 2025). "When WFDC1 expression is down-regulated, those proteases become more active, potentially promoting tumor cells to invade surrounding tissues through enhanced ECM degradation." (PMID 40740240, 2025). "Experimental studies have shown that overexpression of WFDC1 can markedly slow tumor cell growth, and interestingly, WFDC1 is located on chromosomal region 16q24 - a locus known to undergo loss of heterozygosity (LOH) in multiple cancer types." (PMID 40740240, 2025). "SLPI, WFDC2, WFIKKN2, and WFDC1 consistently showed low expression across tumor types, whereas WFDC5, WFDC3, and WFIKKN1 displayed heterogeneous expression profiles." (PMID 40350979, 2025). "Statistical analysis showed significant tumor-specific upregulation of WFDC1, WFDC2, WFDC3, SLPI, PI3, and ANOS1 (P < 0.0001), while WFIKKN1 was notably downregulated in neoplastic tissues (P < 0.0001)." (PMID 40350979, 2025). "By reducing the secretion of these pro-tumor factors, WFDC1 helps maintain the stability of the tumor microenvironment and inhibits tumor progression." (PMID 40740240, 2025). "More clinical studies should also be conducted on other WFDC proteins, such as WFDC12 and WFDC1, exploring their functions, including antiprotease, antibacterial, and tumor suppression." (PMID 39296934, 2024). "A recent study found significantly reduced WFDC1 expression in clinical tumor samples compared to normal prostate tissue, with some tumors exhibiting double WFDC1 deletions." (PMID 39296934, 2024). "Normal mammary fibroblasts express tumor whey acidic protein four-disulfide core domain 1 (WFDC1), which is tumor suppressive and highly expressed in resting fibroblasts but downregulated in CAFs." (PMID 37046676, 2023). "Three of these were intergenic but SNP rs16963349 was intronic to WAP four-disulfide core domain 1 (WFDC1), a possible tumor suppressor gene." (PMID 24376456, 2013). "BEX1, PTGDS, GRIK2 and WFDC1, also in the top 10 downregulated probesets, have all been identified as downregulated in tumours or as inhibitors of cell proliferation in immortalised cell lines." (PMID 24148222, 2013). "Consistent with its tumor suppressor potential, ectopic expression of latexin in C39-8 cells increased expression levels of Maspin or WFDC1 by more than 2 or 3 fold separately." (PMID 21466706, 2011). "Among these, mammary serine protease inhibitor (Maspin) and wap-type four disulfide core 1 (WFDC1) are tumor suppressor candidates with protease inhibitor activity." (PMID 21466706, 2011). "And in terms of this, further exploration of WFDC1’s role in tumor development is warranted." (PMID 39296934, 2024). "Additionally, several tumor related genes, including Maspin, WFDC1, SLPI, S100P, and PDGFRB, were shown to be differentially expressed in MGC803 cells in response to latexin expression." (PMID 21466706, 2011). "Additionally, WFDC1’s ability to inhibit epithelial hyperplasia by regulating COX-2 suggests it could be a valuable tumor suppressor." (PMID 39296934, 2024). "This suggests that WFDC1 transcripts may originate from other nonblood cells, perhaps in the tumor microenvironment, and are then transferred to this subset of platelets." (PMID 39190500, 2024). "Therefore, it is conceivable that WFDC1 and IL-17D, as part of a SORBS2-stablized secretome, could play a crucial role in modulating the polarization of myeloid cells within the tumor microenvironment, which remodel it towards a tumor-suppressive immune milieu." (PMID 29548303, 2018).
cancer (12 papers, 2010 to 2025). A tumor composed of atypical neoplastic, often pleomorphic cells that invade other tissues. "The significant discrepancy in WFDC1’s proposed roles across cancer types warrants further investigation into the underlying tissue-specific mechanistic switches." (PMID 41200167, 2025). "WFDC1 gene is mapped to chromosome 16q24, an area of frequent loss of heterozygosity in many cancers." (PMID 21143783, 2010). "Conversely, SLPI, WFIKKN1, WFDC2, and WFDC1 demonstrated variable prognostic effects across cancer types, suggesting context-dependent, microenvironment-driven functional duality." (PMID 40350979, 2025). "Our results demonstrated that WFDC1 was attenuated while WFDC2 was significantly elevated in carcinoma tissue." (PMID 34301920, 2021). "Enhanced expression of either WFDC1 or IL-17D potently represses SORBS2 depletion-mediated cancer metastasis promotion." (PMID 29548303, 2018). "Downregulation of Maspin and WFDC1 has been found in a variety of cancers." (PMID 21466706, 2011). "It is possible that certain genetic variants affecting WFDC1 expression or function could, in specific environmental or tissue contexts, make this gene act as a cancer-promoting factor rather than a suppressor." (PMID 40740240, 2025). "WFDC proteins have been found to be upregulated in many diseases, such as WFDC1, WFDC2, WFDC12, WFDC14 are upregulated in cancers, inflammatory diseases and so on." (PMID 39296934, 2024). "Specifically, we focused on the pro-cancer immunomodulatory role of SORBS2 and its bound targets WFDC1 and IL-17D." (PMID 29548303, 2018).
infection (2 papers, 2010 to 2011). The state of being infected such as from the introduction of a foreign agent such as serum, vaccine, antigenic substance or organism. "WFDC1/ps20 promotes infection by a method that appears in keeping with a more fundamental biologic role of this factor in promoting cell adhesion and regulation of the extracellular matrix." (PMID 20937128, 2010).
WFDC1 also shares sentences with these, for which no sentence is quoted: brain tumors (1 paper); hematologic diseases (1); hepatocellular carcinoma (1); HIV-1 infection (1); Insulin resistance (1); leukemia (1); Obesity (1); type 2 diabetes (1); virus infection (1); Wilms tumor (1).